TNF (tumor necrosis factor)
Diseases named in the same sentence as TNF in open-access papers (continued):
Sharing a sentence is not in itself a finding about the gene and the disease.
co-infection (continued). "Altogether, our findings suggest that IL-10, IFN-γ, and TNF-α are key cytokines as high levels of IFN-γ and TNF-α contributed to the lethality of disease and IL-10 acted as a protector in the course of B. microti and P. berghei co-infection." (PMID 37492527, 2023). "In the present study, the levels of IL-2, IL-6 and TNF-α were markedly higher, while the level of IL-10 was markedly lower in HIV/HBV coinfection group than those in HBV infection group and control group, suggesting that HIV worsens HBV-induced inflammatory response." (PMID 38357144, 2023). "Excluding co-infection with soil-transmitted helminths, individuals with C. sinensis still had significantly higher antigen-specific IgG and IgE levels, and diminished serum levels of IL-1β, IL-2, IL-4, IL-12p70, IL-17A, IFN-γ and TNF-α." (PMID 36083861, 2022). "To examine whether co-infection alters the induction patterns of cytokines and chemokines, we measured the serum levels of IP-10, MCP-1, TNF-α, IL-1-β, IL-6, IL-10, and IFN-γ over the course of infection using ELISA." (PMID 34711897, 2021). "Co-infection with HIV did not significantly reduce the activation of IFN-γ or TNF-α at Mtb regrowth endpoints, suggesting lack of a generalized immune suppression." (PMID 32373548, 2020). "However, in the co-infection mouse model employing the reduced viral dose, the neutralization of IFN-γ and IFN-γ together with IL-6 had clear effects on the concentrations of TNF-α, CCL-5, IL-1ß, and GM-CSF." (PMID 31474978, 2019). "Finally, cytokines that increased during co-infection when compared to DENV mono-infection were IFN-ω (2.28 fold, p<0.001), TNF-α (1.94 fold, p<0.001) and IL-6 (1.64 fold, p = 0.003)." (PMID 28644900, 2017). "suis co-infection potentiates the up-regulation of IL-6, CCL5 and TNF-α." (PMID 27213692, 2016). "Matrine treatment significantly down-regulated the expression of TLR3, TLR4 and TNF-α although it, to some extent, suppressed p-IκBα expression, suggesting that TLR3,4/NF-κB/TNF-α pathway play an important role of Matrine in combating PRRSV/PCV2 co-infection." (PMID 27080155, 2016). "Interestingly, our data demonstrate that co-infection with C. albicans yeast cells reduces F. nucleatum-induced MCP-1 and TNFα production in RAW macrophages, while hyphal C. albicans does not show such a drastic negative impact." (PMID 27295972, 2016). "Although the pro-inflammatory cytokine TNF-α was not significantly regulated, five tumor necrosis factor receptor superfamily genes were significantly regulated in the co-infection group." (PMID 25906258, 2015). "In general, the observed impaired production of Th1 cytokines (IFN-gamma and IL-2) and pro-inflammatory cytokines (TNF-alpha and IL-6) during HIV co-infection in LTB-infected individuals might favor intracellular Mtb growth and fail to control the conversion of LTBI into ATB." (PMID 39514524, 2024). "Moreover, we found that IL-6 and TNF-α, generally induced by LPS, may promote BTLA expression on CD4+ T cells via the STAT3 and NF-κB signaling, which explains why HBV-ACLF patients with coinfection have elevated BTLA levels." (PMID 38418488, 2024). "Our results suggested that chronic TB might suppress the TNF-α expression or deplete TNF-α-secretion cells, or TNF-α+ cells might be immigrating to the lesion location, which led to the low level of TNF-α+ cells in the peripheral blood of TB and HIV/TB co-infection." (PMID 37483385, 2023). "Some studies also showed lower TNF production and cellular proliferation in MTB-specific peripheral T cells in HIV/MTB co-infection individuals than in individuals with HIV infection, and HIV/MTB co-infected macrophages released fewer TNF-α than macrophages infected with only MTB." (PMID 36619740, 2022).
co-infection (continued). "In addition, co-infection significantly increased the mRNA expression of most pro-inflammatory cytokines tested, including interleukin (IL)-1β, IL-6, IL-8, chemokine (C–C motif) ligand 4 (CCL4), tumor necrosis factor-α (TNF-α) and interferon-β (INF-β)." (PMID 33743838, 2021). "To evaluate the impact of the infection and subsequent TNF-α expression on the production of SP-A, we measured the SP-A protein content by immunofluorescence staining in the human alveolus-on-a-chip model following infection with IAV, S. aureus or co-infection." (PMID 32316261, 2020). "The hypothalamus appeared to be particularly responsive to lung co-infection, as we did not observe any difference in microglial or astrocyte morphology in the hippocampus and whilst TNFα expression was increased, IL-6, IL-1β and CCL-2 expression were unaltered." (PMID 29980196, 2018). "Thus, we are able to identify protective factors in coinfection, such as neutrophils and TNF-α, which are not required for protection from the single mild S. pneumoniae infection employed here." (PMID 26265006, 2015). "Indeed we show, at baseline, that TB+HIV+ individuals displayed a different cytokine expression pattern when compared to TB+HIV− individuals, and co-infection was characterized by elevated IL-4, G-CSF, IFN-γ and TNF-α concentrations and decreased IL-12(p70) and IL-17 levels." (PMID 22606304, 2012). "Finally,the mRNA levels of several cytokines were determined, and showed that the transcription of IFNB1, TNF, IL1B, and OASL was higher in the co-infection group than in the singly infected group, which may have been the consequence of increased PEDV replication." (PMID 37065133, 2023). "Interestingly, non-HIV patients with co-infection and pneumocystosis alone showed lower levels of SP-A, IL-1β, TNF-α, IFN-γ, IL-18, IL-17A, and IL-23 than histoplasmosis patients, suggesting an immunomodulatory ability of P. jirovecii over H. capsulatum response." (PMID 34829225, 2021). "TNF-α was detected irrespective of the subsequent health status and may therefore reflect a response to the introduction of the novel B. hyodysenteriae antigen or a subsequent subclinical co-infection with B. hyodysenteriae or other bacteria, such as E. coli." (PMID 18700003, 2008). "In our study, age, gender, HBV coinfection, CD4+ cell count, platelet count, and TNF-α were not correlated with the odds of death." (PMID 40006998, 2025). "Our findings suggest that the cytokines TNF-α, IL-1β, and IFN-γ are central to the immune response in HIV-CC co-infection whereas others like IL-18 are not." (PMID 40046043, 2025). "Among mice treated with nor-NOHA, HIV co-infection significantly suppressed several human cytokines and chemokines, including MCP-1, MCP-3, TNF-α, MIP-3A, and GM-CSF." (PMID 38922041, 2024). "The relationship between immune exhaustion markers (PD-1/PD-L1) and apoptotic markers such as Fas/FasL, TGFβ1, TNF-α, and Th1/Th2 cytokines are not clearly delineated in HBV/HIV coinfection." (PMID 30815625, 2019). "In conclusion, our study provides evidence that the combination of Th1 cytokines [IFN-γ, TNF-α, IL-2 and IL-12(p70)] have a potential to discriminate between culture-positive and -negative pulmonary tuberculosis with HIV co-infection." (PMID 31086619, 2018). "Significantly higher levels of systemic and local interleukin-6 (IL-6), tumor necrosis factor alpha (TNF-α) and IL-1β have been found during the early stages of co-infection than during single infection, regardless of the morphogenesis of C. albicans." (PMID 28666415, 2017). "Although levels of TNF-α and IL-6 following mono-infections were donor and MOI-dependent; production of these cytokines was significantly augmented during co-infections and this was not attributed to the increase in total MOI." (PMID 28644900, 2017). "The frequency of MTB-specific CD4+ tri-functional T-cells secreting IFN-γ, IL-2 and TNF-α was independent of both mycobacterial burden and HIV co-infection." (PMID 26756579, 2016).
co-infection (continued). "MTB-specific CD4+ functional effector cells secreting IFN-γ alone, TNF-α alone or IFN-γ and TNF-α more frequently expressed CD127 compared with EBV and/or CMV-specific cells in those without evidence of HIV co-infection." (PMID 26417433, 2015). "Serum concentrations of TNF-α, IL-6, IL-10 and TGF-β1 were measured, separately, in healthy controls and in patients with HIV-HCV coinfection, distributed in two groups, those without and those with liver cirrhosis." (PMID 23840511, 2013). "Other cytokines including TNFα, IL-1β and IFN-β were also induced by IAV and SP; however, no significant change in expression was found following co-infection." (PMID 23421931, 2013). "It is possible that TNF-α and IL12p70 produced by macrophages compensates the suppressed anti-mycobacterial activity of HIV MDSC, but inhibition of monocyte/macrophage function by MDSC observed in tumors cannot be ruled out in HIV-M tuberculosis co-infection." (PMID 33995365, 2021). "In addition, we assessed inflammatory gene expression in the hippocampus, and whilst TNFα was significantly increased in co-infected mice, IL-6, IL-1β and CCL-2 were not altered by single- or co-infection treatment." (PMID 29980196, 2018). "HIV coinfection did not change IL-10, IFN-α, TNF, or IFN-γ presence within excised LNs." (PMID 27462092, 2016). "In those without HIV co-infection PPD-specific CD4+ cells secreting IFN-γ with or without TNF-α and expressing CD127 were relatively more frequent but this expression was reduced in HIV co-infection indicating that these cells might be relatively short-lived." (PMID 26417433, 2015).
dementia (180 papers, 2008 to 2026). Loss of intellectual abilities interfering with an individual's social and occupational functions. "Although the exact causes of dementia remain multifactorial and complex, oxidative stress (reactive oxygen species), neuroinflammation (TNFα, IL-6, and IL-1β), and inflammasomes are considered central mechanisms in its pathology." (PMID 40277934, 2025). "Elevated TNF-α levels have been linked to the progression from MCI to dementia and have been implicated in adverse effects on functional connectivity in brain regions involved in spatial processing, memory, and language." (PMID 40711681, 2025). "The inhibition of TNF-α holds potential as a therapeutic strategy to prevent AD and enhance cognitive function in populations at elevated risk for dementia." (PMID 41586222, 2025). "Anti-TNF therapies are popular treatments for RA, and recent findings indicate that controlling this inflammatory signaler can significantly reduce dementia risk." (PMID 39860337, 2025). "Most studies indicate that patients treated with TNF inhibitors have a lower risk of dementia than those treated with conventional synthetic DMARDs (csDMARDs)." (PMID 40291023, 2025). "In their study, TNF-α was strongly correlated with lower scores on cognitive tests and an increased risk of developing dementia, highlighting the impact of inflammation on neuropsychological health." (PMID 40137151, 2025). "In contrast, treatment with TNF inhibitors has been associated with improvements in cognitive function and a lower risk of dementia." (PMID 40291023, 2025). "The adipose tissue is an endocrine organ, capable of secreting inflammatory cytokines, such as interleukin-6 (IL-6), and tumor necrosis factor-α, which are associated with an increased risk of dementia." (PMID 39861366, 2025). "Studies have shown that levels of inflammatory markers, such as TNF‐α, IL‐6, and C‐reactive protein, elevate before the manifestation of clinical symptoms associated with various types of dementia, including AD and vascular dementia." (PMID 38482136, 2024). "In the present study, the effect of IL1B, MIR146A and TNF on dementia or AD susceptibility confirmed previously published data." (PMID 36829875, 2023). "The potential inhibition of TNF-α with pharmacological strategies paves the way for preventing AD and improving cognitive function in people at risk for dementia." (PMID 38201258, 2023). "Among inflammatory genes, polymorphisms in IL1B and TNF showed a protective function in the development of dementia or AD, while MIR146A was associated with CSF biomarkers." (PMID 36829875, 2023). "Subjects who were heterozygous for TNF rs1800629 polymorphism were less likely to have dementia (p = 0.017, OR = 0.368 (0.163–0.834))." (PMID 36829875, 2023). "We identified the strongest interactions between combinations of SNPs (IL-6 rs1800796, TNFα rs361525, and IFNγ rs2069705) associated with the risk of suffering from dementia." (PMID 36389080, 2022). "A meta-analysis supported the association between the TNF-α rs361525 polymorphism and dementia risk involving different ethnic groups." (PMID 36389080, 2022). "The association of CSF TNFα levels with the incidence of dementia were evaluated using Cox proportional hazards regression analysis adjusted for potential confounders." (PMID 36288380, 2022). "Our finding that CSF TNFα was associated with the risk of incident dementia is in line with previous studies." (PMID 36288380, 2022). "At the present study, we aimed to investigate the association of CSF TNFα and its related receptors with the risk of developing dementia among MCI subjects." (PMID 36288380, 2022). "Of the estimated genotypic pools, individuals with homozygous alleles for the IL-1α (rs1800587), IL-6 (rs1800796), TNFα (rs361525), and IFNγ (rs2069705) genes were identified in the high-risk group for dementia." (PMID 36389080, 2022).
dementia (continued). "In conclusion, we found that high CSF TNFα levels were associated with the risk of conversion to dementia among MCI subjects." (PMID 36288380, 2022). "Elevated levels of TNF-α are also associated with age-related diseases such as dementia and heart disease, and this was indeed one of the few cytokines that were consistently detected to be basally increased across multiple aged macrophage populations assayed." (PMID 34390567, 2021). "Incident dementia was associated with increases in all five serum cytokines during the follow-up, and the strength of the significance remained for TNF-α, IL1-α, and IL-1β after applying the Bonferroni correction." (PMID 30510525, 2018). "Several population-based studies have shown that peripheral inflammatory cytokines, especially IL-6, TNFα, and IL-1β, are correlated with the risk of dementia." (PMID 27340344, 2016). "With regard to HIV-1 infection, studies have shown association of TNF-α -308A allele with HIV-1-associated dementia and other HIV therapy related complications like Lipodystrophy Syndrome in infected patients." (PMID 24837009, 2014). "Persistent microglial activation releases cytokines such as IL-1β and TNF-α, creating a neuroinflammatory milieu that drives the synaptic dysfunction and oxidative stress—processes implicated in both MS neurodegeneration and various dementias." (PMID 41602975, 2026). "Likewise, SLE literature involves the antiphospholipid antibodies and TNF-α in the cerebrovascular and dopaminergic impairment, putting dementia and PD at risk." (PMID 40842786, 2025). "It is also reported that some medications used in RA management may also contribute to this susceptibility, although tumor necrosis factor (TNF) inhibitors show promising results in decreasing dementia risk." (PMID 39813219, 2025). "Additionally, the TNF-α released from microglia, in conjunction with IL-6, has been linked to late-onset dementia and a greater risk of dementia." (PMID 39104536, 2024). "In addition, we identified two inflammatory biomarkers associated with incident dementia, tumor necrosis factor-α (TNF-α) and monocyte chemotactic protein-1 (MCP-1)." (PMID 35563811, 2022). "In addition, supra-physiological TNF-α was found to trigger dementia through both early and late pathogenic mechanisms." (PMID 35957121, 2022). "Indeed, a role for TNFα in subcortical white matter damage in HIV-associated dementia has been proposed since 1993 based on TNFα quantification in postmortem brain tissue." (PMID 34067023, 2021). "Many observations have linked TNF-α and its receptors to dementia pathogenesis." (PMID 33434745, 2021). "If this were the case, this model organism may be used to test therapeutic approaches, including reduction of TNF-α activity and glutamatergic transmission, targeting early pathogenic mechanisms leading to dementia." (PMID 32579116, 2020). "Interestingly in human centenarians dementia is associated with high levels of circulating TNF-α levels and suggests a role of TNF-α in age-associated brain pathology." (PMID 27115072, 2016). "In addition, inhibiting the expression of TLR4, a receptor on microglia, reduces microglial activation and the release of inflammatory cytokines, including IL-6, TNF-α, and IL-1β, alleviating the chronic neuroinflammation associated with AD and other dementias." (PMID 40872491, 2025). "Additionally, TNF-α together with other cytokines (e.g., IL-6) associate aging and dementia." (PMID 32802484, 2020). "Among biological agents, the group using non‐TNF blocker had a significantly lower incidence of dementia (HR 0.37, 95% CI 0.21‐0.65, p= 0.0005)." (PMID 40542608, 2025). "A previous study in nVS PWH with dementia identified elevated levels of TNFα expression in the brain and astrogliosis; however, we did not observe an association between levels of TNFα and the frequency GFAP+ astrocytes in our cohort." (PMID 40469287, 2025).